CAV1 (caveolin 1)
Diseases named in the same sentence as CAV1 in open-access papers (continued):
Sharing a sentence is not in itself a finding about the gene and the disease.
cancer (continued). "Cav1 is a growth suppressor protein, although its level is often elevated in advanced cancer, suggesting the oncogenic switch to the role in growth progression." (PMID 25821797, 2015). "Considering the significance of Cav-1 in nutrient delivery and cancer development, emerging studies are underscoring the role of Cav-1 in regulating cancer metabolism." (PMID 26431273, 2015). "The mechanism in cancer cells is as follows: caveolin-1 is downregulated and production of NO is increased by oxidative stress." (PMID 26690480, 2015). "There is growing evidence of a role of epigenetic mechanisms in regulating CAV1, particularly in cancer." (PMID 26112043, 2015). "We therefore used PC3 PCa cells that lack PTRF and caveolae but express Cav1 and pCav1, to specifically determine the role of PTRF in Cav1-Gal3 regulation of FA dynamics and cancer cell migration." (PMID 25942420, 2015). "Although the underlying mechanisms of Cav-1 fluctuation during cancer progression are unclear, studies to better understand the therapeutic and prognostic values of Cav-1 for cancer—especially for chemosensitivity and chemoresistance—are underway." (PMID 26431273, 2015). "Systemic administration of anti-Cav-1 antibody for three weeks to mice orthotopically injected with Cav-1-secreting PCa cells decreases cancer cell volume in lymph nodes." (PMID 26328273, 2015). "Current evidence also explains why Cav-1 expression is restored in metastatic or drug-resistant cancer cells." (PMID 26431273, 2015). "To date, most of the reports of epigenetic effects on CAV1 are related to DNA methylation and in the context of cancer." (PMID 26112043, 2015). "Downregulation of caveolin-1 has been previously shown to sensitize cancer cells to ionizing radiation." (PMID 26065715, 2015). "A greater understanding of Cav-1 and its role in modulating drug resistance will help us understand cancer therapy and discover better chemotherapeutics." (PMID 26431273, 2015). "The RhoA/ROCK pathway and Caveolin-1 (Cav-1) participate in the process of tumorigenesis in numerous types of cancer." (PMID 26066055, 2015). "Meanwhile, increased Cav-1 expression has been reported in other drug-resistant cancer cells, such as SKVLB1 cells resistant to vinblastine, HT-29 cells resistant to colchicine and MCF-7 cells resistant to adriamycin." (PMID 26431273, 2015). "Plasminogen and caveolin-1 attracted special attention, as both have already been described to be involved in anchorage independent growth of cancer cells." (PMID 26633361, 2015). "Cav-1 overexpression was frequently confirmed in advanced cancer stages and positively associated with ABC transporters, cancer stem cell populations, aerobic glycolysis activity and autophagy." (PMID 26431273, 2015). "Here, we summarize current evidence of a relationship between Cav-1 and cancer drug resistance, discuss pathophysiological implications of this pathway and propose a targeted therapeutic strategy." (PMID 26431273, 2015). "Combined targeted therapy should be considered when designing novel treatment strategies based on Cav-1 to overcome cancer metastasis or drug resistance." (PMID 26431273, 2015). "Cav-1 silencing was reported to result in activation of these survival signals and promote cancer transformation and initiation." (PMID 26431273, 2015). "Meanwhile, exogenous elevation or knockdown of Cav-1 expression confirmed a critical role for Cav-1 in mediating cancer chemosensitivity." (PMID 26431273, 2015). "Taken together, an improved understanding of Cav-1 regulation and its role in chemosensitivity modulation is required to improve cancer prevention and therapy." (PMID 26431273, 2015). "Treatment with 5-AZA has been shown to restore CAV1 expression in some cancers confirming hypermethylation." (PMID 26112043, 2015).
cancer (continued). "It has recently been shown that the stroma of several human carcinomas, such as breast, colorectal and kidney, as well as that of metastatic melanomas, is enriched in CAV1-expressing CAFs." (PMID 25633184, 2015). "Caveolin-1 (Cav-1), a protein comprising the portions of membranes called caveolae, was previously shown to have a potentiating effect on the progression of cancers." (PMID 24955034, 2014). "Histological analysis of subcutaneous Cav-1-overexpressing tumors by H&E staining showed a classical cancer cell morphology including the condensation of heterochromatin and the presence of multinucleated cells, an indicator of mitotic dysfunction." (PMID 24939878, 2014). "These CSCs, which were found to overexpress tumor promoter caveolin-1 (Cav-1), displayed aggressive cancer phenotypes of apoptosis resistance and enhanced cell invasion and migration compared with their non-CSC counterpart." (PMID 24939878, 2014). "Others and we have reported the potentiating action of Cav-1 on cancer aggressiveness and metastasis." (PMID 24955034, 2014). "On the other hand, increasing evidence demonstrates that caveolin-1 suppresses the transformed phenotype of cancer cell." (PMID 25397596, 2014). "Taken together, these results reveal a novel molecular pathway in the regulation of cancer cell migration via Cav-1 and Akt pathways." (PMID 24955034, 2014). "While in malignant neoplasms the expression of caveolin-1 is decreased, in benign tissue it is either increased or ‘normal’ levels of the protein are registered; this observation is also confirmed by the results of our study." (PMID 24533441, 2014). "Caveolin-1 (CAV1) has significant roles in many primary tumors and metastasis, despite the fact that malignant cells from different cancer types have different profiles of CAV1 expression." (PMID 25180681, 2014). "Vascular endothelial growth factor receptor-2 (VEGFR-2) and Cav-1 are frequently colocalized, suggesting an important role played by this interaction on cancer cell survival and proliferation." (PMID 24738074, 2014). "The clinical value of Cav-1 expression in other types of cancer, including bladder, nasopharynx, oral, colorectal, esophagus, ovarian, bone and cerebral cancer, have also been reported." (PMID 25202343, 2014). "In order to target the clinical value of Cav-1 expression in human cancer cells, this study reviewed the progress of present clinical studies on several types of human cancer." (PMID 25202343, 2014). "The current review of previous studies lead to the recognition of a contradictory theory with regard to the expression of Cav-1 in breast, gastric, hepatic and oral cancer." (PMID 25202343, 2014). "CAV1 has been reported to be up-regulated by the DNA methyltransferase inhibitor 5-AZA-2′-deoxycytidine (5-aza-dC) in several types of cancer." (PMID 25313138, 2014). "The caveolin 1 influences cancer formation, progression, and prognosis, but this influence is not so sharp, in spite of recent results that have clarified many roles." (PMID 24591761, 2014). "Both the SCP2 and BSG branches share the same CAV1 upstream regulators such as MAPK3, TNFRSF1B, and GNAI2, which have been implicated in cancer cells death pathways." (PMID 24949431, 2014). "The aberrant regulation and expression of CAV1 is involved in the pathogenesis of a variety of cancers." (PMID 25148256, 2014). "Cav-1 plays an important role in regulating the behaviour of cancer cells including anoikis resistance in NSCLC by the interaction with its antiapoptotic partner." (PMID 25015569, 2014). "Here, we discuss recent findings and novel concepts that support a role for caveolin-1 in cancer development and its distant spreading." (PMID 23521716, 2013). "Overall Cav1 is a promising target for selective cancer diagnosis and therapy as modulator of intracellular signalling." (PMID 23521716, 2013).
cancer (continued). "It is known that the phosphatidylinositol 3-kinase (PI3K)/Akt pathway is a major survival pathway in human cancers and is regulated by caveolin-1." (PMID 24143228, 2013). "Using pharmacological and genetic approaches, the present study revealed that Cav-1 plays a key role in inhibition of cancer-endothelium adhesion by attenuating hydrogen peroxide and hydroxyl radical generations after cell detachment." (PMID 23460862, 2013). "Along with the observation that Cav-1 decreased in a time-dependent fashion after cell detachment, we found that at later-time points, cancer-endothelium adhesion significantly increased the concomitant of that Cav-1 depletion." (PMID 23460862, 2013). "We examined the expression levels of CIC/CSC related markers including ALDH1, OCT4, NANOG, SOX2 and Caveolin-1 in the intralymphatic cancer cells to evaluate their relationship to lymph node metastasis." (PMID 24376714, 2013). "Cav-1 overexpressed, Cav-1 knockdown, and H460 cells were detached and subjected to endothelial adhesion assay and the cancer cells adhering on the HUV-EC-C endothelial cells were observed." (PMID 23460862, 2013). "Recently, caveolin-1 (Cav-1), a 21–24 kDa integral membrane protein, has garnered increasing attention as its role in the regulation of cancer cell behaviors has been revealed." (PMID 23984323, 2013). "Together, these results indicate that extended NO exposure has a novel effect on cell migration through a Cav-1-dependent mechanism, a finding that strengthens our understanding of cancer biology." (PMID 23984323, 2013). "While the exact mechanisms are still being investigated, several proteins including FAK, Akt and Cav-1 have been shown to control motility in cancer cells." (PMID 23874694, 2013). "The knowledge regarding the role of caveolin-1 (Cav-1) protein on endothelium adhesion of cancer cells is unclear." (PMID 23460862, 2013). "Altered expression of epithelial or stromal caveolin-1 (Cav-1) is observed in various types of human cancers." (PMID 23527097, 2013). "To study the role of Cav-1 protein on cancer cell adhesion, we first detached the cancer cells to mimic the early step of metastasis, and evaluated the expression profile of Cav-1 after cell detachment over times." (PMID 23460862, 2013). "Recently, Cav-1, a major protein of the plasma membrane domain named caveolae, has been reported to potentiate cancer cells’ ability to resist anoikis and to migrate and invade." (PMID 23874694, 2013). "The present study revealed that Cav-1 plays a negative regulatory role on cancer-endothelium interaction." (PMID 23460862, 2013). "Recently, roles of caveolin-1 (Cav-1) in regulation of cancer progression and metastasis in various types of cancer have been revealed and such a protein perhaps received the most attention in cancer-related research." (PMID 23460862, 2013). "To confirm that Cav-1 attenuates cancer cell adhesion to endothelial cells, we explored the effect of different ectopic Cav-1 expression levels on H460 cells adhesion to endothelium." (PMID 23460862, 2013). "Increased ERK-1/2 signalling can promote the expression of Cav-1 in various human cancer cell lines including those derived from the prostate and smooth muscle." (PMID 24119769, 2013). "Cav-1 is a multifunctional protein and it has received increased consideration in cancer because of its role in cell survival and in drug resistance." (PMID 23613870, 2013). "In contrast, Cav-1 was shown to potentiate cancer progression and increasing evidence has indicated its role as a cancer promoter." (PMID 23460862, 2013). "We and others have suggested the important role of Cav-1 in rendering cancer cells resistant to anoikis after cell detachment, enhancing invasion and migration, and facilitating growth in anchorage-independent manner." (PMID 23460862, 2013).
cancer (continued). "In summary, we show here that caveolin-1 expression enhances velocity, directionality and persistency of migration of metastatic cancer cells and that this effect depends on the presence of tyrosine-14." (PMID 22505999, 2012). "Cav-1 is an interesting molecule because of its apparent paradoxical biological functions in malignant tumors." (PMID 22200856, 2012). "Anti-oxidants (N-acetyl cysteine, NAC), quercetin and the anti-diabetes drug metformin) or autophagy inhibitors (chloroquine) will suppress the destruction of caveolin-1 in stromal fibroblasts and inhibit cancer growth." (PMID 23006971, 2012). "Expression of CAV1 in cancer cells stimulates the formation of long, branched tubules derived from the plasma membrane (up to 50 μm)." (PMID 23272165, 2012). "In contrast, in cancer cells expressing both CAV1 and cavin-1, shorter tubules are visible, indicating that cavin-1 limits the ability of CAV1 to form tubules." (PMID 23272165, 2012). "In some cancer cells, the coordination between these proteins is lost, resulting in antagonistic effect between CAV1 and cavin-1." (PMID 23272165, 2012). "Our findings contribute to explain, at the molecular level, the role of caveolin-1 in drug resistance of cancer cells." (PMID 22745744, 2012). "The aims of this study were to assess expression of Src, Cav-1 and RhoGD12 in relationship to cancer-specific survival, and to examine the potential interrelationships between these markers." (PMID 22353809, 2012). "Although this protein was originally identified as a membrane protein, Cav-1 has also been reported to be present in the secretory cellular components of the pancreas and salivary glands, in differentiating osteoblasts and in cancer cells." (PMID 22040717, 2011). "In order to maximize treatment benefits, we will need to develop new biomarkers (like stromal Cav-1) to predict which cancer patients will respond best to anti-oxidant therapy." (PMID 21605374, 2011). "The role of caveolin-1 (cav-1), the main structural protein of caveolae, in cancer progression and invasion is contradictory and appears to depend upon the cancer type and stage of progression." (PMID 21199580, 2011). "The 2 studies also revealed that caveolin-1 is an essential regulator of the invadopodia-mediated degradation of ECM, which indicates that caveolin-1 plays an essential role in cancer cell invasion." (PMID 21307399, 2010). "A comparison of the Cav-1 (-/-) stromal cell gene set with other existingtranscriptional profiles also shows significant overlap with ER-negative humanbreast cancer (p = 8.96 x 10-10; BRCA_ER_NEG)." (PMID 20442453, 2010). "Clinical studies showed that the increased expression of caveolin-1 is correlated with the presence of metastasis and poor prognosis in several human cancers." (PMID 21307399, 2010). "Recently, it was demonstrated that expression of Cav-1 promotes survival of cancer cells following treatment with ionizing radiation (IR), further supporting Cav-1 as a stress protector in malignant cells." (PMID 20700465, 2010). "Although accumulating evidence indicate that expression of Cav-1 is altered in a stage-dependent manner during progression of various types of cancers, the precise roles of Cav-1 in cancer development, progression, and treatment remain to be fully defined." (PMID 20700465, 2010). "Existing data has shown that BPBC is associated with high expression of Cav-1 and EMT of cancer cells is dependent upon the presence of Cav-1." (PMID 20540763, 2010). "Okamoto and colleagues showed that long-term EGF treatment reduced expression of Cav-1 in cancer cells; and subsequently up-regulated snail and down-regulated E-cadherin expression." (PMID 20540763, 2010). "Taken together, blocking the functions of lipid rafts and caveolin-1 should be an approach to targeting invadopodia-mediated cancer cell invasion." (PMID 21307399, 2010).
cancer (continued). "Caveolae and cav-1 have been described to play prominent roles in various human disease phenotypes including cancer (for reviews)." (PMID 19763272, 2009). "Here we will consider, more specifically, the data concerning the ambiguous roles ascribed to caveolin-1 in signal transduction and cancer." (PMID 18400052, 2008). "Despite several studies on caveolins in cancer, especially CAV1, their role in cancer development and progression is still contentious." (PMID 18612310, 2008). "In primary cancer cells, where E-cadherin is often still expressed, caveolin-1 exerts its anti-proliferative and pro-apoptotic properties, but in highly metastatic cells from colon or melanoma, this ability is lost." (PMID 18400052, 2008). "A number of clinicopathological studies have shown a positive correlation between caveolin-1 overexpression and advanced cancer disease, metatasis and poor prognosis (for critical review see Williams and Lisanti, 2005)." (PMID 18283322, 2008). "Although the specific mechanism by which caveolin-1 facilitates cancer progression is still unclear, the strong correlation with vascular invasion suggests that caveolin-1 contributes to angiogenesis and metastasis." (PMID 18283322, 2008). "Bortezomib, an antibody against the 26-S-proteasome, has been shown to target Caveolin-1 among a variety of other proteins in studies in various cancer entities." (PMID 17915016, 2007). "Among these cancers, Caveolin-1 expression is upregulated compared to expression levels in non-inflammatory carcinomas." (PMID 17915016, 2007). "Recent evidence suggests a role for cav-1 in promoting cancer cell migration, invasion and metastasis; however, the molecular mechanisms have not been described." (PMID 15969750, 2005). "Caveolin-1 and -2 protein expression levels were also suppressed in cancer tissues compared to normal tissues by Western blotting." (PMID 15305200, 2004). "Consistent with this the chromosomal loci of caveolin-1 and -2 has been recently identified as 7q31.1, a fragile site frequently deleted in a wide spectrum of human cancers that includes cases of sporadic RCC." (PMID 14612902, 2003). "Caveolin-1 was expressed both on the cell membrane and in the cytoplasm of cancer cells, as evidenced by the presence of stained granular immunoreaction products." (PMID 12402154, 2002). "The caveolin-1 gene is located at human chromosome 7q31.1, and this region is frequently deleted in carcinomas." (PMID 11953823, 2002). "This indicates the possibility that caveolin-1 not only inhibits but also stimulates carcinoma progression and metastasis." (PMID 11953823, 2002). "An additional more important finding is that caveolin-1 expression significantly decreased in undifferentiated (anaplastic) carcinomas." (PMID 11953823, 2002). "On the other hand, the results of studies for caveolin-1 expression using human carcinoma tissue have been different from those using cell lines." (PMID 11953823, 2002). "Notably, genes including CAV1, ITGB1, BNIP3, and YTHDF2 were associated with the AKT signalling pathway, suggesting a functional link between ODC1 activity and cancer progression." (PMID 41803527, 2026). "However, the roles of CAV1 in cellular physiology and in complex diseases like cancer, cardiovascular diseases, and metabolic disorders extend beyond the structural scaffolding of caveolae, and are particularly notable for its context-dependent nature." (PMID 40332409, 2025). "Additionally, while inhibition of Cav‐1 alleviates MS, it accelerates cancer progression, underscoring the need for targeted strategies that account for cell type, disease stage, and the presence of other comorbidities in patients." (PMID 40778471, 2025). "Beyond promoting cancerous traits, Cav1 modulates EV dynamics to support cancer progression." (PMID 40963741, 2025).